PMEL (premelanosome protein)
Description:
Forms physiological amyloids that play a central role in melanosome morphogenesis and pigmentation. The maturation of unpigmented premelanosomes from stage I to II is marked by assembly of processed amyloidogenic fragments into parallel fibrillar sheets, which elongate the vesicle into a striated ellipsoidal shape. In pigmented stage III and IV melanosomes, the amyloid matrix serves as a platform where eumelanin precursors accumulate at high local concentrations for pigment formation. May prevent pigmentation-associated toxicity by sequestering toxic reaction intermediates of eumelanin biosynthesis pathway. Represents a potent melanoma-specific antigen. Among melanoma non-mutated self-peptides, G9-154 (KTWGQYWQV), G9-209 (ITDQVPFSV) and G9-280 (YLEPGPVTA), appear to act as immunodominant common epitopes that stimulate anti-tumor immune response mediated by HLA-A-restricted cytotoxic T cells.
Synonyms: ME20M; D12S53E; PMEL17; SILV; SI; gp100; HMB-45; ME20; HMB45; ME20-M; P1; P100; SIL
Tractability: Antibody: UniProt places it where antibodies can reach, with high confidence; its Gene Ontology location is reachable by antibodies, with high confidence; UniProt predicts a signal peptide or a membrane-spanning region. Other modalities: an approved drug acts on it.
Gene: Protein-coding gene on chromosome 12 (55,954,104 to 55,973,317, reverse strand). Ensembl gene ENSG00000185664.
Subcellular location: Endoplasmic reticulum membrane; Golgi apparatus, cis-Golgi network membrane; Endosome, multivesicular body; Melanosome; Extracellular vesicle; Secreted
Subcellular location (Human Protein Atlas): Endoplasmic reticulum; Golgi apparatus
Pathways (Reactome):
Developmental Biology: Regulation of MITF-M-dependent genes involved in pigmentation
Gene Ontology:
Molecular function: identical protein binding; protein binding
Biological process: melanosome organization; eye development; positive regulation of melanin biosynthetic process
Cellular component: cis-Golgi network membrane; endoplasmic reticulum; endoplasmic reticulum membrane; extracellular exosome; extracellular region; extracellular vesicle; Golgi apparatus; melanosome; melanosome membrane; multivesicular body membrane; multivesicular body, internal vesicle; plasma membrane; multivesicular body
Genetic constraint (gnomAD): Loss-of-function variants: 48 observed, 63.24 expected, observed/expected ratio (o/e) 0.76, 90% interval 0.6 to 0.96. The upper end of that interval is the gene's LOEUF score, 0.96, which puts it in group 4 of 6, group 1 being the genes least tolerant of losing a copy. Missense variants: 703 observed, 842.96 expected, observed/expected ratio (o/e) 0.83, 90% interval 0.78 to 0.89. Synonymous variants: 294 observed, 326.67 expected, observed/expected ratio (o/e) 0.9, 90% interval 0.82 to 0.99.
Homologues: Orthologues: chimpanzee PMEL (99% identical), macaque PMEL (95% identical), pig PMEL (80% identical), rabbit PMEL (79% identical), dog PMEL (77% identical), mouse Pmel (75% identical), rat Pmel (75% identical), guinea pig PMEL (74% identical), tropical clawed frog pmel (38% identical), zebrafish pmela (34% identical), zebrafish pmelb (30% identical). Paralogues in human: GPNMB (26% identical), TMEM130 (12% identical).
Diseases named in the same sentence as PMEL in open-access papers:
PMEL is named in the same sentence as 211 diseases in open-access papers, as found by Europe PMC text mining. Sharing a sentence is not in itself a finding about the gene and the disease. The quoted sentences say what the papers report.
melanoma (1,064 papers, 1996 to 2026). A malignant, usually aggressive tumor composed of atypical, neoplastic melanocytes. "We also report a spliced variant of the well-characterized melanoma-specific protein PMEL (sPMEL), which exhibits superior antigen abundance, tumor specificity, and recurrence across patients." (PMID 40672284, 2025). "Briefly, we use transgenic PMEL mice, wherein all CD8+ T cells are specifically reactive to the melanoma-associated antigen gp100, expressed by the B16-F10 tumor cell line." (PMID 38636457, 2024). "A link between amyloid proteins and cancer has also been established in melanoma where the amyloidogenic protein PMEL is currently used as a diagnostic marker." (PMID 38199984, 2024). "The widely-used diagnostic PMEL antibodies for human malignant melanoma like HMB45 are known to only recognize epitopes requiring specific glycans." (PMID 32668786, 2020). "In that respect, apoptotic bodies released by mouse B16-F1 melanoma cells showed enrichment of the melanoma tumor-associated premelanosome protein (PMEL)." (PMID 31086060, 2019). "For instance, CD63 is directly involved in the ESCRT-independent sorting of premelanosome protein (PMEL) in human melanoma cells." (PMID 40575159, 2025). "S-100 is a calcium-binding protein expressed by melanoma cells; Melan-A is a melanoma-associated antigen, and HMB-45 is a monoclonal antibody that targets the premelanosome protein gp100." (PMID 40422036, 2025). "Melanoma gp100 antibody (PMEL) positive immunostaining further confirmed the presence of melanocytes within SKOs." (PMID 39822647, 2025). "The most frequently used antigen in CanVaxKB, PMEL/gp100, plays an important role in the proliferation of melanocytes and is a natural target of melanoma vaccines." (PMID 38204924, 2024). "HLA peptides from MDAs, such as DCT, PMEL and tyrosinase were recurrently detected exclusively in melanoma and melanocytes." (PMID 39835134, 2024). "Four region-specific marker genes (PMEL for melanoma region, COL1A1 for stroma region, CXCL10 for lymphoid tissue 2, and MS4A1 for lymphoid tissue 1) were identified from the ST data to demonstrate the accuracy of imputed expression." (PMID 39402626, 2024). "Conversely, the expression levels of CRALBP (cellular retinaldehyde-binding protein, a visual cycle marker) and PMEL (also named melanoma) were significantly increased in hiPSC-RPE cells." (PMID 38229139, 2024). "For the malignant melanoma cells, PMEL, IFITM1, HSPA1A, DUSP1, FOS and TMSB4X are the shared driver genes across three subtypes in S4 File." (PMID 38096269, 2023). "Pre-melanosome protein (PMEL; PMEL17; glycoprotein 100, gp100) ordinarily plays a role in melanin synthesis and is highly specific to melanoma." (PMID 38067178, 2023). "The gp100 antigen (also known as premelanosome protein, PMEL) is an intracellular transmembrane glycoprotein enriched in melanosomes and B16 melanoma cells." (PMID 36106631, 2022). "This transcription factor that promotes the expression of the most melanogenic proteins including TYR, TYRP1, DCT and PMEL, was found to be also critical for melanoma invasion and proliferation upon down-regulation in melanoma cells." (PMID 36776379, 2022). "Meanwhile, we also turned to TCGA Skin Cutaneous Melanoma (SKCM) database to analyze the correlation between CD27-AS1 level and the expressions of MITF, TYR and PMEL in melanoma." (PMID 35096622, 2021). "PMEL is a melanocyte-specific marker known to be a melanogenesis gene and is used in the pathological diagnosis of melanoma." (PMID 33564068, 2021). "TAAs like PMEL/gp100, tyrosinase, and several CT Ags have been identified as melanoma regression Ags." (PMID 32582212, 2020). "We found that Pmel+ cells recognized Pmel-17 (mouse homologue of human PMEL (also known as gp100)) in mouse melanoma, and GD2-CAR T cells recognized GD2, a disialoganglioside expressed in tumours of neuroectodermal origin." (PMID 32694789, 2020).
melanoma (continued). "First, clinically relevant melanoma marker molecules PMEL and MLANA were detected in all cells and found significantly down-regulated in the YDFR-CB variant." (PMID 31892524, 2020). "17-AAG induced differentiation by increasing protein levels of tyrosinase and PMEL/gp100 (premelanosome protein/glycoprotein 100) in both BRAF-mutated and wild-type BRAF melanoma cell lines." (PMID 31659567, 2020). "Strikingly, we found little off-target expression of SOX2 (neuronal precursor cells) or PMEL (melanoma cells) in D32 transplanted organoids compared to controls, suggesting that transplantation diminished off-target cells." (PMID 31784515, 2019). "Additional tumor-associated antigen (TAAs) derived HLA ligands are frequently identified by MS, such as “normal” (wild-type) proteins overexpressed or restricted to tumors (e.g., MelanA, Tyrosinase, PMEL in melanoma; NY-ESO in multiple cancer types)." (PMID 31440238, 2019). "In a premelanosome protein (Pmel-1) mouse model, ACT using gp100-specific T cells caused ocular damage, which paralleled the findings in human melanoma patients who received gp100-specific TCR-T therapy." (PMID 31852498, 2019). "Briefly, we utilized CD8 T cells from PMEL mice, which contain a T cell receptor specific to the gp100 antigen expressed in B16-F10 melanoma cells." (PMID 30400835, 2018). "Antibodies against melanoma markers, such as anti-gp100/PMEL and PNL2 are used to identify LAM lesions." (PMID 25978616, 2015). "We have used the expression of the melanoma markers gp100/PMEL and PNL2-antigen as an indicator of the presence of LAM cells." (PMID 25978616, 2015). "For CD63 and PMEL, the GO term GO:0006583 (melanin biosynthetic process) and its associated genes TYR and DCT were positively associated, suggesting activation of the tyrosine-to-melanin conversion pathway in the Melanoma-A region." (PMID 41279463, 2025). "Immunohistochemistry showed no gp100 loss in melanoma metastases, and previously reported PMEL decreases were likely due to melanocyte loss rather than transcriptional downregulation." (PMID 40311102, 2025). "PMEL TRM-like cells, which recognize GP100 melanoma antigen, were incubated with B16F10 cells." (PMID 39671478, 2024). "The results confirmed that a number of TCRs matched known MART1-reactive clonotypes but also revealed matching TCRs that might recognize other melanoma antigens, such as PMEL and MAGEA1." (PMID 39312285, 2024). "Recently, PMEL has also been proposed as a prognostic marker for a poor overall survival of melanoma patients, but its role in melanoma development or progression is largely unknown." (PMID 38199984, 2024). "Additionally, BACE2 cleaves the pigment cell–specific melanocyte protein (PMEL) and controls pigmentation in zebrafish and mice and, partly, hair pigmentation in humans as well as PMEL-dependent melanoma metastasis formation." (PMID 38888964, 2024). "Specifically, we found novel splicing in melanocyte-specific transmembrane glycoprotein (PMEL) in the melanoma cell lines, which was further confirmed by qPCR and may be crucial for cancer proliferation and, thus, be targeted by novel therapeutic approaches." (PMID 36768787, 2023). "Briefly, CD8 T cells from pmel-1 TCR transgenic mice (PMEL T cells), which are specific for the gp100 antigen expressed by B16-F10 mouse melanoma cells, were activated and expanded ex vivo and then tethered with IL-12 before adoptive transfer into mice bearing B16-F10 tumors." (PMID 35476449, 2022). "In addition, we identified Mesenchyme (COL1A1+), Endothelium (SOX18+, KDR+), proliferating cells (TOP2A+, MKI67+), and some off‐target cells; Glial (MSX1+, SOX2+), Melanoma (PMEL+, PLP1+), and Neuron (DLL3, HES6)." (PMID 35322595, 2022). "However, we noted that while MITF expression was similar in primary tumors and metastases, a number of well‐characterized MITF target genes (e.g., TYR, TYRP1, MELANA, PMEL) were significantly more highly expressed in primary melanomas than in metastases." (PMID 35771179, 2022).
melanoma (continued). "Primary in situ melanoma tissues were immunostained for PMEL (SILV) using the HMB45 antibody." (PMID 33564068, 2021). "Moreover, several other cancer-related proteins (NRAS, Src, c-Met, c-Kit, EGFR, MCAM, annexin A1, HAPLN1, LGALS1, GALS3, NT5E, and PMEL) were detected in MTEX originating from various melanoma cell lines." (PMID 32709086, 2020). "Therefore, PMEL, which is also known as gp100, ME20, PMEL17, and silver, is a melanoma-specific glycoprotein that plays an important role in the development of melanin bodies by forming a proteolytic fibrous matrix for melanin deposition." (PMID 31156710, 2019). "Tumours in 129/Sv mice stained negatively for the melanoma marker protein PMEL (the HMB45 antigen)." (PMID 29731980, 2018). "In vitro, hAAT upregulated melanocytic differentiation markers (MITF, TYR, PMEL, MART-1) and increased melanin production in murine and human melanoma lines, suggesting enhanced tumor immunogenicity." (PMID 41594664, 2026). "Consistently, the mRNA expression of MITF-regulated melanogenic genes, including tyrosinase, TRP-1, PMEL, and TRP2/DCT, was significantly downregulated in fisetin-treated melanoma cells." (PMID 41373883, 2025). "In the same PLN74 cell line, guadecitabine treatment strongly downmodulated expression of three differentiation proteins (MITF, GP100/PMEL, MART-1), as evaluated by quantitative digital pathology on melanoma cell cytospins." (PMID 40682094, 2025). "Compared to C3, C1/C2/C4 subpopulations showed higher metastasis feature, including melanoma invasion marker genes MITF and PMEL, which were highly expressed in C1/C2." (PMID 40866912, 2025). "For decades, the pathological diagnosis of melanoma has been using glycoprotein 100 (gp100), a product of the PMEL gene and a protein of the melanosome membrane, as a marker, and the HMB45 antibody is used to detect it." (PMID 40361349, 2025). "p < .05, including well‐known melanoma markers like MLANA, PMEL (HMB45) and multiple members of the S100 protein family." (PMID 41017066, 2025). "By qPCR for two markers of differentiated melanomas (MITF and PMEL) we identified MITF/PMELHI, MITF/PMELINT and MITF/PMELLO cell lines." (PMID 40682094, 2025). "In our previous work, we discovered that metastatic melanoma cells secrete different amyloidogenic proteins such as APP and PMEL, and proteins that assist amyloidogenesis such as APOE, SORT1, and QPCT." (PMID 38199984, 2024). "Oxidized MART and PMEL proteins, as well as native counterparts, were used as vaccines to immunize C57BL/6 mice prior to challenge with B16F10 melanoma cells." (PMID 38958560, 2024). "The melanoma markers MLANA (MART-1), TYR, HMB45 (PMEL), SOX10, S100, and the proliferation marker MIB-1, which recognizes the Ki67 antigen, are used to diagnose primary and metastatic melanoma." (PMID 37762707, 2023). "Conversely, overexpression of wild-type (WT) MITF in non-melanoma 293T cells increased GREB1 Is4, PMEL, and MLANA mRNAs." (PMID 37658191, 2023). "Such CTLs can be activated by melanocyte-specific antigens PMEL (a premelanosome protein) and MART-1 (a melanoma antigen recognized by T cells)." (PMID 36655287, 2023). "In this context, melanoma cell lines display strong melanocytic features, such as upregulation of melanocytic antigens MART-1 (also known as MLANA) and gp100 (also known as PMEL) and increase in MITF expression." (PMID 36551603, 2022). "First, we identified tumor cells by inferred large-scale CNVs from single-cell expression profiles and newly identified PMEL, S100B, SERPINE2, TYR, and PRAME as marker genes for melanoma malignant cells." (PMID 35646893, 2022). "Antibodies against CD3, CD20, and HMB45 plus S100B were used for VM and used to segment the ROI in B cells (CD20), T cells (CD3), and melanoma cells (PMEL/S100B), and the tumors were categorized into tumors with and without TLS." (PMID 35847846, 2022).
melanoma (continued). "Collagen stiffness induced the expression of melanoma differentiation genes TRPM1, PMEL, TYR and MLANA, as well as well as the proliferation and survival genes CDK2 and BCL2A1." (PMID 36135194, 2022). "Significant difference in antibody response to epitopes of known melanoma antigens CSPG4 (#4), PMEL (#6) and TGO1 (#31) was noticeable between PEM-Mel and MelVac and their respective control groups (Wilcoxon Rank Sum test, p < 0.001)." (PMID 35603273, 2022). "We also examined the transcription of melanin synthesis genes TYR, TYRP1, PMEL, MLANA and DCT by RNAseq analysis in M14 human melanoma cells in which we have disrupted TXNRD1 using Crispr/Cas9 (M14TXNRD1+/− cells)." (PMID 36291795, 2022). "Compared to other melanocytic proteins, such as MART-1 and PMEL, the expression of SLC45A2 in normal melanocytes was shown to be less than 2%, resulting in a significantly improved melanoma-to-melanocyte CTL killing index." (PMID 35267523, 2022). "Melanoma-A consisted of CD63, PMEL, and S1000A1, while Melanoma-B consisted of S100B, FTH1, and AEBP1 expression." (PMID 33535416, 2021). "Disruption of VEGF/VEGFR-2 signaling by simultaneous transfer of CAR T cells expressing anti-VEGFR-2 and T cells specific for gp100 (PMEL), TRP-1 (TYRP1), or TRP-2 (DCT) significantly eradicated B16 melanoma tumors in mice." (PMID 29682521, 2018). "Several biochemical markers are already clinically used to monitor progression and relapse of melanoma, such as S100B, MART1 and PMEL and S100A13." (PMID 25874936, 2015). "In addition, fisetin significantly decreased mRNA levels and suppressed the expression of MITF, tyrosinase, TRP-1, TRP-2, and PMEL in both melanoma and α-MSH-stimulated melanoma cells." (PMID 41373883, 2025). "Protein expression levels of known melanoma markers, such as MITF, MLANA, PMEL, TYR, and SOX10, had the lowest expression in EC-Mit samples (ANOVA, FDR < 6 × 10−4) and had a significantly lower expression in the EC-like subtypes when compared to the Mit-like subtypes." (PMID 40075679, 2025). "Among these, T cells recognize known melanoma antigens such as MART1, PMEL, and MAGEA1, as well as unknown sequences that might be neoantigens." (PMID 39312285, 2024). "Since TYR, TYRP1, TYRP2, PMEL, and MELAN-A are recognised as melanocyte differentiation antigens (MDAs), inhibition of BRAF V600E increases MDAs expression, through the upregulation of MITF, enhancing melanoma immunogenicity." (PMID 37627054, 2023). "Because PMEL is broadly overexpressed (61–90%) in melanoma patients, independent of their stage of disease progression, PMEL is of especially great interest as a therapeutic target." (PMID 38067178, 2023). "Furthermore, among the top 25 genes highly correlated with GREB1 gene expression in melanoma, 16 genes were known targets of MITF, such as MLANA and PMEL." (PMID 37658191, 2023). "PMEL, S100B, SERPINE2, TYR, and PRAME were highly expressed in tumor cells and could be the marker genes for melanoma." (PMID 35646893, 2022). "All four known melanoma cell markers were candidate cell marker genes for cell type H, and MLANA, PMEL, and TYR were candidate cell marker genes for cell type G. In addition, the protein-coding gene PMEL was a candidate cell marker gene for five cell types (all cell types except C, D, and F)." (PMID 34784909, 2021). "Four known melanoma cell marker genes, MITF, MLANA, PMEL and TYR, were obtained from CellMarker." (PMID 34784909, 2021). "While several serum biomarkers are investigated in melanoma patients, diagnostic markers currently applied in clinics are restricted to S-100, HMB-45, Melan-A, and SM5-1, and the prognostic markers to monitor melanoma progression are S100B, MART1, PMEL, and S100A13." (PMID 33302400, 2020).